VIM (vimentin)
Diseases named in the same sentence as VIM in open-access papers (continued):
Sharing a sentence is not in itself a finding about the gene and the disease.
cancer (continued). "The flow cytometry analysis showed that the expression of Vimentin was also elevated in cancer associated fibroblasts (> 99%)." (PMID 34405010, 2021). "Overexpression of vimentin and loss of E-cadherin expression was correlated with increased cancer invasiveness and metastasis." (PMID 34439333, 2021). "Features of EMT are the gain of mesenchymal markers, such as vimentin and N‐cadherin, and the loss of epithelial cell‐junction proteins, such as E‐cadherin, in subsets of cancer cells." (PMID 34047479, 2021). "During the development of EMT in malignant tumors, epithelial cell markers (e.g., E-cadherin) are decreased, in contrast, mesenchymal cell markers (e.g., Vimentin) and EMT-associated transcription factors (e.g., β-catenin) are increased." (PMID 34970490, 2021). "During cancer development, the increase in vimentin protein expression is usually associated with the progression, aggressiveness, and invasive capacities of the disease." (PMID 34198671, 2021). "The deep sequencing of the different types of cancer genome has shown large number of mutations in vimentin." (PMID 34638469, 2021). "Specifically, the expression of ezrin was associated with epithelial cells (i.e., carcinoma cells), compared to the mesenchymal expression of vimentin (i.e., stroma cells/fibers)." (PMID 34198671, 2021). "In this study, the Vimentin amount of tumors was associated with a growth of grade and stage of cancer, as well as with cancer progression to metastasis stage Vimentin increased." (PMID 32665775, 2020). "Through maintaining heterotypic cancer cell–cancer‐associated fibroblast interactions during collective invasion, Vimentin was required for LUAD metastasis." (PMID 31901223, 2020). "As a consequence, surrogate markers for EMT, e.g., loss of E-cadherin expression or increased vimentin expression were used in cancer tissue." (PMID 32630033, 2020). "Loss of E‐cadherin (epithelial marker) and acquisition of vimentin (mesenchymal one) are consistently observed during development and cancer EMT." (PMID 33133573, 2020). "In CRCs, the loss of E-cadherin and gain of vimentin are implicated in cancer progression, and metastasis and are associated with a poor prognosis." (PMID 32218208, 2020). "The overexpression of vimentin has been demonstrated to be associated with an increased migratory or invasive capacity of the cancer cells." (PMID 31968004, 2020). "The EMT process, which is characterized by the loss of E-cadherin and gain of Vimentin expression, is frequently activated during cancer invasion and metastasis in TNBC." (PMID 32850439, 2020). "The loss of E-cadherin and concomitant gain of vimentin expression is indicative of cells having undergone an epithelial to mesenchymal transition, which is often associated with more aggressive forms of cancer." (PMID 33153119, 2020). "Twist-1 has been shown to promote the expression of both N-cadherin and vimentin whose expression has been associated with increased migratory and invasive ability in several cancers." (PMID 32695811, 2020). "Src inhibition induces in breast cancer cells a reverted epithelial phenotype associated with an increase of E-cadherin and a decrease of vimentin and it blocks cancer cell migration." (PMID 32498343, 2020). "A vimentin targeting DNA aptamer NAS-24 caused apoptosis of cancer cells and reduced adenocarcinoma tumors in mice." (PMID 31940801, 2020). "Epithelial-mesenchymal transition (EMT) is characterised by increased levels of snail, MMP14, cadherin-11 and vimentin and is associated with cancer invasion and metastasis." (PMID 32694700, 2020). "Vimentin expression in this study was suggested as a potential biomarker to identify responsive cancer cell populations associated with an EMT phenotype." (PMID 32498343, 2020). "Acquisition of mesenchymal markers, such as N-cadherin, snail, and vimentin, in carcinoma cells promotes the EMT with concomitant loss of epithelial E-cadherin, a major constituent of the adherens junctions." (PMID 32111094, 2020).
cancer (continued). "In mice with primary lung tumor, vimentin is required for metastasis and loss of vimentin is seen in lower grade carcinomas." (PMID 33171868, 2020). "Given that the EMT process is associated with cancer cell invasion, we tested the impact of altered miRNA-328-5p expression on the relative levels of E-cadherin, Snail, and Vimentin expression in HCC cells by Western blot." (PMID 31776329, 2019). "Oxidative stress caused by HIF-1 regulates vimentin gene transcription, which helps in the formation of invadopodia during cancer cell invasion and migration." (PMID 31766246, 2019). "In carcinoma, invasion and metastasis are associated with transition of cancer cells form an epithelial keratins-expressing phenotype to a mesenchymal vimentin (Vim)-expressing phenotype." (PMID 30915272, 2019). "PPM1H knockdown in CRC cells and growth in the corresponding conditional medium increased VIM expression and colon fibroblast proliferation, indicating a transformation of cancer-association fibroblasts (CAFs)." (PMID 30988394, 2019). "Epithelial-mesenchymal transition (EMT) is a genetic program aberrantly activated in various cancers that is characterized by the loss of cell-cell adhesion protein E-cadherin and the acquisition of mesenchymal biomarkers such as N-cadherin, Vimentin and mmp2." (PMID 30940151, 2019). "Vimentin is overexpressed in many cancers and its overexpression is frequently associated with an increased migratory and invasive capacity." (PMID 30894168, 2019). "For long time, high expression of VIM was only associated with poor prognosis in patients with different cancers." (PMID 31552188, 2019). "The ability of ajoene to covalently bind to Cys-328 of vimentin in cancer cells, causes the filaments become condensed and disrupted." (PMID 30894168, 2019). "Clinically, the loss of E-cadherin and increased expression of Vimentin are significantly associated with poor prognosis in a variety of cancers." (PMID 31197076, 2019). "We found that EMT-associated factors including vimentin, Snail, and zinc finger E-box binding homeobox 1 were upregulated in cancer cells overexpressing ERRα/PGC-1α and that transforming growth factor-beta (TGF-β) was induced in T-HESCs in the same conditions." (PMID 31040369, 2019). "At both time points, cancer-associated stroma was positive for vimentin, α-smooth muscle actin (α-SMA) and D2-40, while it was negative for CD34." (PMID 30765891, 2019). "In this review, we draw from recent studies focused on three IF proteins most associated with cancer (keratins, vimentin, and nestin) to highlight how several “hallmarks of cancer” described by Hanahan and Weinberg are impacted by IF proteins." (PMID 31126068, 2019). "In summary, the vimentin expression in various types of cancer cells and in cancer-associated fibroblasts appears to be associated with malignancy and drug resistance." (PMID 30248895, 2018). "Loss of epithelial E-cadherin and gain of mesenchymal vimentin often correlate with increased invasive behaviour and are used as markers of cancer progression." (PMID 30560881, 2018). "EMT is a key process driving cancer metastasis and the loss of E-cadherin and increase in vimentin expression are considered to be the most important molecular markers of EMT." (PMID 29375271, 2018). "The association of vimentin expression with increased metastasis and invasion ability has been reported for many cancers including lung, prostate, and gastric cancers." (PMID 29720982, 2018). "In 5-Aza treated cells, the expression of cancer associated invasive markers was tested (E-Cadherin, N-Cadherin, Vimentin, Twist, MMP-2, and MMP-9)." (PMID 29695771, 2018). "While control cells were minimally invasive, E-Cadherin loss and Vimentin upregulation resulted in a significant increase in both motility and invasiveness in cancer cells pretreated with t1 and t2 exosomes." (PMID 29854876, 2018).
cancer (continued). "The observation that hyperphosphorylation of intermediate filaments can be linked to numerous diseases including cancer, has indicated that the phosphorylation status of vimentin can be important for health and diseases." (PMID 30248895, 2018). "Immunofluorescence (IF) staining of E-cadherin and vimentin in PCa cells essentially confirmed the potency of SPINK1 in causing an EMT in recipient cancer cells." (PMID 30333494, 2018). "Vimentin is the most well-known hallmark of mesenchymal phenotype in cancers, which is upregulated through β-catenin/TCF complex." (PMID 28334027, 2017). "In both early and aggressive cancer cell types, loss of Runx1 expression paralleled decreases of the epithelial marker E-cadherin, while the mesenchymal marker Vimentin was highly expressed only in the MCF10CA1a cells." (PMID 28407681, 2017). "EMT is an essential step for cancer cell to acquire migration and invasion ability; loss of E-cadherin and increase of vimentin are surrogate markers for cell migration and invasion in EMT process." (PMID 29234409, 2017). "And overexpression of AXL is closely associated with expression of EMT-related proteins, such as vimentin, in various cancer models." (PMID 29259259, 2017). "Expression of EMT marker vimentin is usually associated with a more mesenchymal-like and dedifferentiated state of the cancer cell." (PMID 28225793, 2017). "In cancer, vimentin expression is associated with the transition from a more differentiated epithelial phenotype to a dedifferentiated state." (PMID 28225793, 2017). "Increased expression of cytokeratin and vimentin is associated with development and progression of cancers." (PMID 27190522, 2016). "This is consistent with the role of Plectin in association with vimentin in providing a scaffold for invadopodia, facilitating cancer cell invasion and metastasis." (PMID 27470985, 2016). "It has been reported that epithelial-mesenchymal transition (EMT) is an essential step for cancer metastasis, which is characterized by loss of epithelial markers like E-caderin and increase of mesenchymal markers such as Vimentin." (PMID 26839961, 2016). "Many cancer cell lines exhibit both a vimentin-based and a keratin-based IF network that underlines distinct intracellular organization and regulation." (PMID 27412958, 2016). "SCEL knockdown also caused cancer cells to form more invasive structures within 3D cultures, increased the mesenchymal marker vimentin, and attenuated the epithelial marker E-cadherin." (PMID 27013588, 2016). "These genes included ANKLD1, AXL, CAV1/2, LDHB, ETS1, IFI16, PTRF (cavin), KIAA1199 and VIM, which have previously been linked to drug resistance in breast and other cancers." (PMID 26646320, 2016). "We applied mPADs to measure the contractile force directly from the cell bottom of vimentin deficient cancer cells." (PMID 25965826, 2015). "Simultaneously, up-regulated mesenchymal marker vimentin expression was associated with highly invasive and metastatic properties along with the expression of cancer stem cell (CSC) markers." (PMID 26452130, 2015). "As another well-known marker of EMT, several studies have shown that the abnormal expression of vimentin was present in many kinds of epithelial tumors and associated with the invasion and metastasis of cancer cells." (PMID 26702618, 2015). "It should be noted however, that TSGA10IP (TSGA10 interacting protein) interacts with TSGA10, a protein also associated with cancer and that binds cytoskeletal proteins (e. g., vimentin and actin-γ1)." (PMID 26569114, 2015). "EMT is characterized by the loss of cell polarity, down-regulation of epithelial proteins most prominently ECAD, and up-regulation of the mesenchymal protein, VIM, which has more recently been implicated in promoting carcinoma invasion and metastasis." (PMID 26010068, 2015).
cancer (continued). "Several studies have shown that TGF-β1 can induce JNK phosphorylation, and constitutively active JNK can cause cancer cell migration and invasion, and induces the expression of mesenchymal-specific markers, vimentin and fibronectin." (PMID 25337707, 2014). "Vimentin has been previously linked to the metaplastic potential of cancer cells as its increased expression has been demonstrated to be a marker of epithelial mesenchymal transition (EMT)." (PMID 24502646, 2014). "In the majority of cancers vimentin is overexpressed and associated with a metastatic phenotype and a poor prognosis for the disease outcome." (PMID 24392146, 2014). "In fact, high levels of VIM expression in cancer patients are correlated with a poor prognosis and, the simultaneous expression of VIM and CK in BC cells seems to be associated with lower survival rates in BC patients." (PMID 25277187, 2014). "Comparing levels of IDO1 mRNA within the TCGA data set (n = 748) revealed a significant positive correlation of IDO1 mRNA levels with vimentin expression (a hallmark of basal cancers)." (PMID 25091696, 2014). "Genetic alteration and morphological changes are modulated during cancer metastasis, such as loss of epithelial cell identity (e.g., occludin and EpCAM) and acquisition of mesenchymal features (e.g., vimentin and TWIST1)." (PMID 24039787, 2013). "Vimentin has also been implicated in cancer cell invasion and high levels of this protein are associated with poor treatment outcome in patients with cancer." (PMID 24282534, 2013). "Epithelial-mesenchymal transition (EMT) is a process by which cancer cells acquire mesenchymal properties, such as induction of vimentin, while epithelial-associated genes like E-cadherin are lost." (PMID 26889270, 2013). "High levels of vimentin are associated with a poor prognosis and vimentin has been identified as a possible target for molecular cancer therapy." (PMID 24282534, 2013). "Inhibition of vimentin filament integrity causes mesenchymal cells to adopt an epithelial shape and downregulation of vimentin expression has been shown to impair carcinoma cell migration and adhesion." (PMID 23295955, 2013). "In cancer, altered vimentin level is associated with a dedifferentiated phenotype, increased motility, invasiveness, and poor clinical prognosis." (PMID 22110952, 2011). "While ectopic expression of miR-200 caused up-regulation of E-cadherin in cancer cell lines and reduced their motility, its inhibition reduced E-cadherin expression, increased expression of vimentin and induced EMT." (PMID 20615238, 2010). "Downmodulation of CD146 expression in the MDA-MB-231 cell line resulted in downmodulation of vimentin, as well as of a set of genes that include both genes associated with a poor prognosis in a variety of cancers and genes known to promote cell motility." (PMID 19123925, 2009). "Vimentin, a major intermediate filament protein of mesenchymal cells, was found to be over-expressed in some human cancer tissues and associated with prognostic indicators." (PMID 18445260, 2008). "In addition to MC-encoded molecules being transferred to CRC cells, MC coculture also induced the expression of cancer cell-encoded EMT-related markers as demonstrated by coculture inducing expression of the HT-29 cell-encoded VIM-promoter mCherry reporter." (PMID 41039118, 2025). "Furthermore, β-catenin is a central component of the Wnt signaling pathway, modulating the transcription of several downstream genes such as MMPs, c-Myc, cyclin D1, and vimentin, which has been implicated in cancer progression and therapeutic resistance." (PMID 41304843, 2025). "These authors suggested that regular tea consumption can suppress metastasis through downregulation of miR-483-3p, which upregulates vimentin expression and downregulates E-cadherin expression, since these events are associated with cancer invasiveness and metastasis." (PMID 41296402, 2025).
cancer (continued). "Additionally, vimentin is associated with various human diseases, including cataracts, cancer, Crohn’s disease, and HIV." (PMID 40061451, 2025). "The study suggests that sWRE's inhibition of cell motility may involve the disruption of vimentin, a protein associated with aggressive cancers and metastasis." (PMID 40584407, 2025). "Given vimentin’s role in both the metastasis of cancer cells and susceptibility to bacterial infections, exploring the modulation of vimentin may be a viable strategy for achieving both anticancer and antibacterial therapeutic effects." (PMID 40061451, 2025). "While vimentin is generally associated with AS, its specificity is limited as it may also be expressed in carcinomas." (PMID 40666093, 2025). "Although vimentin expression is strongly associated with cancer metastatic potential, the exact role of vimentin in cancer metastasis and the underlying mechanism of its pro-metastatic functions remain unclear." (PMID 38915055, 2024). "EMT typically initiates metastasis during cancer progression, during which epithelial cells acquire migration and invasion characteristics, and MMPs’ expression increases, with the loss of E-cadherin and gain of N-cadherin and Vimentin." (PMID 38672844, 2024). "Enriched CTCs were then analyzed in three steps by flow cytometry: (i) removing dead cells, (ii) isolation of CD45(−) PanCK(+) cells as CTCs, and (iii) analysis of CTCs producing CD90, CD133, EpCAM, or vimentin, which are proteins associated with cancer progression." (PMID 39108869, 2024). "Moreover, the combination inhibits epithelial-mesenchymal transition (EMT) progression and reduces cancer cell invasion by restoring E-cadherin and β-catenin expressions and loss of vimentin, major biomarkers of EMT." (PMID 38431613, 2024). "Elevated level of Vimentin has been detected in aggressive epithelial cancers, and is closely associated with an increased likelihood of metastasis and poor prognosis across various types of cancers, including NPC." (PMID 38191501, 2024). "FTO, implicated in various cancer types, including GC, might influence the m6A modification status of transcripts related to vimentin expression, affecting their stability and translation." (PMID 38685125, 2024). "Authors have described the enrichment of globosides in cancer cells characterized by E-cadherin expression, while elevated levels of genes encoding the biosynthesis of gangliosides were observed in cells expressing mesenchymal markers, namely vimentin." (PMID 39084491, 2024). "The Western blotting analysis further confirmed the result that QD605-labeled LY-1 aptamer was capable of binding to a subpopulation of HCCLM9 cells, with a higher amount of CK19 and Vimentin presented, which are the protein markers associated with cancer migratory and invasiveness." (PMID 37670975, 2023). "Moreover, it was revealed that loss of STK24 inhibited expression of cyclin D and vimentin and promoted expression of E-cadherin in the cancer cells." (PMID 36720310, 2023). "The transcription factors SNAIL, SLUG, and ZEB1 are key regulators of EMT by modulating the expression levels of E-cadherin, N-cadherin, vimentin, and other proteins, and their increased expression is associated with poor outcomes and aggressive disease in many types of cancer." (PMID 37508550, 2023). "It has been proposed that some vimentin-positive cells could be circulating cancer-associated fibroblasts (cCAF)." (PMID 37176111, 2023). "Since vimentin is key to the migratory phenotype and is implicated in chemoresistance and tumorigenicity, it is therefore a therapeutic clinical target to decrease metastatic potential of cancer cells." (PMID 36701406, 2023). "However, overexpression of vimentin is also considered as a hallmark of EMT in cancer cells and was found to induce a senescent cell morphology in fibroblasts." (PMID 37855367, 2023).